SNORA60 (small nucleolar RNA, H/ACA box 60)
Synonyms: ACA60
Gene: Small nucleolar RNA gene on chromosome 20 (38,449,370 to 38,449,503, forward strand). Ensembl gene ENSG00000199266.
Gene Ontology:
Biological process: RNA processing
Cellular component: nucleolus
Homologues: Orthologues: chimpanzee SNORA71 (100% identical), macaque SNORA71 (99% identical), pig SNORA71 (90% identical), rabbit SNORA60 (90% identical), rat Snora60 (87% identical), guinea pig SNORA60 (86% identical), mouse Gm25129 (84% identical), dog SNORA71 (81% identical), dog SNORA71 (74% identical). Paralogues in human: SNORA71D (82% identical), SNORA71C (81% identical), SNORA71A (79% identical), SNORA71E (70% identical), SNORA71 (69% identical), SNORA71 (67% identical).